IFITM1 (interferon induced transmembrane protein 1)
Diseases named in the same sentence as IFITM1 in open-access papers (continued):
Sharing a sentence is not in itself a finding about the gene and the disease.
infection (116 papers, 2010 to 2026). The state of being infected such as from the introduction of a foreign agent such as serum, vaccine, antigenic substance or organism. "Overall, we found that BST2, ZBP1, CXCL11, and IFITM1 are associated with infection with SARS-CoV-1, SARS-CoV-2 WA-1 and Omicron BA.1, hepatitis C virus, HIV, and influenza virus." (PMID 39874350, 2025). "Following infection with both low and highly pathogenic avian influenza (LPAI/HPAI) strains, duck IFITM1/2/3 are highly upregulated in the lungs and the ileum from day 1 post-infection, whereas only IFITM3 was modestly upregulated in the ileum of chickens." (PMID 33810083, 2021). "Ifitm1−/− mice showed significant weight loss on day 7 after infection compared to wild-type littermates (P < 0.05)." (PMID 30567988, 2019). "We recently reported that HIV-1BH10 became resistant to IFITM1 restriction in the spread infection through acquiring mutations in viral Env and Vpu proteins that together enhance the virus transmission between cells." (PMID 25738301, 2015). "We provide the first report of a detailed immunological analysis of Ifitm1 deficient mice towards an infection challenge." (PMID 23115618, 2012). "While individual knockdown of IFITM1 or IFITM3 significantly increased infection, combined knockdown of both IFITM1 and IFITM3 boosted infection to a much greater extent." (PMID 42262132, 2026). "At the transcript isoform level, the canonical isoform IFITM1–202, was dramatically upregulated after infection relative to uninfected controls (p = 2.7e-37)." (PMID 41542048, 2026). "JEV-E signals were detected in the cytoplasm, the presence of exogenous IFITM1 expression reduced the infection rate of JEV." (PMID 40723864, 2025). "BST2, ZBP1, CXCL11, and IFITM1 were involved in protein binding, and they are also broadly engaged in biological processes related to IFNs and responding to infections." (PMID 39874350, 2025). "The expression of IFITM1 in these 2D organoids was also verified via immunofluorescence staining prior to infection with PEDV-HM." (PMID 40353666, 2025). "Following infection with high-titre virus (multiplicity of infection: 1,000) for 3 h, IFITM1 knockdown cells showed approximately three times more EBV copies than controls." (PMID 38649412, 2024). "After 72 h of EBV exposure, flow cytometry displayed a reduction in the infection rate of over 50% (~3% to 1.5%) upon IFITM1 overexpression." (PMID 38649412, 2024). "TVs expressing sgRNAs targeting known RFs like TRIM5, IFI16, IFITM2, SAMHD1, GBP5 and IFITM1 were enriched after 15 and 20 days post-infection confirming that targeting RFs provides a selection advantage to the respective viruses." (PMID 38714682, 2024). "We observed that Ifitm1, Ifitm2, Ifitm3, Ifitm5 and Ifitm6 were highly upregulated during NF1_LV infection while only Ifitm1, Ifitm3, Ifitm6 were upregulated during NF45_HV exposure and at a lower level." (PMID 39735262, 2024). "In fact, IFITM1 was localized at the AiV RNA replication sites early in infection, suggesting its involvement in cholesterol accumulation there." (PMID 37252940, 2023). "In ducks, IFITM1 was highly upregulated after infection with HPAI H5N1, whereas little response was seen in chickens, further suggesting it is a contributory factor to resistance." (PMID 36992300, 2023). "For ST1, inhibition of infection by IFITM1, IFITM2 and the IFITM3 43AS mutant, which shows broader subcellular localization than IFITM3, was significant." (PMID 36851478, 2023). "Early in infection, steady-state level of IFITM1, together with viral proteins, would enable efficient RNA replication by transporting cholesterol to the AiV RNA replication sites." (PMID 37252940, 2023). "Levels of IFITM1 expression tended to be lower among patients with severe pandemic influenza A(H1N1) who succumbed to the infection compared to survivors." (PMID 35708622, 2022).
infection (continued). "It is interesting to see that IFITM1 has already been known to inhibit multiple infections with other enveloped viruses, including coronavirus." (PMID 35601483, 2022). "Then, the expression of CSFV Npro was assessed by Western blotting in IFITM1/2/3-knockdown cells at 24 h and 48 h post-infection with CSFV." (PMID 36205528, 2022). "As expected based on previously published work, overexpressed IFITM1, -2, and -3 all protected cells significantly (decreasing infection to 50% to 75% of that with vector only)." (PMID 36197088, 2022). "IFITM1, 2, and 3 restricted infection at the level of alphavirus glycoprotein-mediated entry, both in the context of direct infection and cell-to-cell transmission." (PMID 34078739, 2021). "In IFN-α-treated IFITM1/2/3 knockout cells, infection nearly reached levels of control-treated sgNT-transduced cells." (PMID 34933450, 2021). "A549 IFITM1/2/3 KO - ACE2 cells stably expressing IFITM3 constructs were used for the infection studies." (PMID 34981045, 2021). "Again, IAV-LP infection was strongly enhanced by IFITM1/2/3 knockout in both IFN-α- and control-treated HUVEC, while MLV-LP was not affected." (PMID 34933450, 2021). "The most potent effect of IFITM1/2/3 knockout was observed with IAV-LP infection, which was increased in both IFN-α- and control-treated cells." (PMID 34933450, 2021). "The IFITM family consists of IFITM1, 2, 3, 5, and 6, which can block the replication and infection of enveloped viruses." (PMID 33711920, 2021). "The increased disease severity observed in IFITM1-deficient mice following infection with HRSV highlights the ability of IFITM1 to modulate infection in vivo." (PMID 33276587, 2020). "IFITM1- to -3-transduced Vero cells were infected with different members of the Paramyxoviridae and Pneumoviridae, and infection was compared to that in Vero cells transduced with an empty vector." (PMID 30567988, 2019). "To explore the role of IFITM1 in enveloped DNA viruses that can enter the cell via the plasma membrane, we looked at the effect of IFITM1 expression on infection by HSV-1, a member of the Alphaherpesvirinae." (PMID 30567988, 2019). "Ifitm1−/− mice and wild-type C57BL/6 mice were intranasally infected with RSV A2 and monitored daily for weight loss for 7 days after infection." (PMID 30567988, 2019). "Here we demonstrate that IFITM1 can inhibit infection with a range of viruses that enter via the plasma membrane." (PMID 30567988, 2019). "Here we show that in vitro, IFITM1 inhibits infection by several RNA viruses that enter via the plasma membrane, including mumps virus, RSV, human metapneumovirus (HMPV), and a DNA virus, herpes simplex virus 1 (HSV-1)." (PMID 30567988, 2019). "Cell lines expressing the IFITM1 AA-63, -69, -76, or -83 mutant showed increased infection relative to cells expressing wild-type IFITM1, suggesting an impairment of IFITM-mediated restriction." (PMID 30567988, 2019). "IFITM1 also restricted infection with an enveloped DNA virus that can enter via the plasma membrane, herpes simplex virus 1 (HSV-1)." (PMID 30567988, 2019). "Overexpression of wild-type IFITM1 reduced infection for all tested viruses, relative to empty cells." (PMID 30567988, 2019). "Overexpression of IFITM1 prevented infection by a number of Paramyxoviridae and Pneumoviridae, including respiratory syncytial virus (RSV), mumps virus, and human metapneumovirus (HMPV)." (PMID 30567988, 2019). "IFITM1 restricted infection of all the viruses tested, including parainfluenza virus (PIV), RSV, HMPV, Newcastle disease virus (NDV), and mumps virus." (PMID 30567988, 2019). "Taken together, we demonstrate for the first time a crucial role for IFITM1 in the in vivo infection of γ-herpesviruses." (PMID 30237526, 2018).
infection (continued). "On the contrary, a majority of genes sequenced at the IgM peak highlight progression towards greater liver damage and infection; such as Humanin (down-regulation), IFITM1 (down-regulation), CYP2A5 (down-regulation), and Alpha-2HS-glycoprotein (up-regulation)." (PMID 30279404, 2018). "We went one step further in demonstrating that over-expressing IFITM1 significantly alters not only the internalization of the γ-herpesviruses but also the ability to establish infection as monitored by the expression of the respective viral transcripts." (PMID 30237526, 2018). "Herein, we provide pioneering evidence to demonstrate a key role for IFITM1 in the in vitro and in vivo infection of γ-herpesviruses." (PMID 30237526, 2018). "The expression of IFITM1 increased in virus infected cells as early as 5 min post infection (PI) which was elevated by 10 min and 15 min PI in BJAB, but significantly declined by 30 min PI." (PMID 30237526, 2018). "To authenticate the role for IFITM1 in enhancing infection of γ-herpesviruses, we tested the effect of silencing IFITM1 on the internalization of the viruses." (PMID 30237526, 2018). "The KR/AA mutant IFITM1 executed increased activity to inhibit the infection by Jaagsiekte sheep retrovirus (JSRV) and 10A1 amphotropic murine leukemia virus (MLV)." (PMID 30687247, 2018). "We noticed that infection by the dual tropic HIV-1 89.6 in U87.CD4.CCR5 cells was almost equivalently inhibited by IFITM1 and IFITM2; however, IFITM3 still exhibited the strongest inhibition among all three IFITMs." (PMID 30087232, 2018). "The results implicate the ability of γ-herpesviruses to induce the expression of IFITM1 during early stages of infection." (PMID 30237526, 2018). "In the current study, we demonstrated that EBV, another γ-herpesvirus, induces IFITM1 expression during the early stages of infection and it followed an identical pattern as that of KSHV." (PMID 30237526, 2018). "A natural model system to explore the effect of IFITM1 on gammaherpesvirus infection in vivo is infection of BALB/c mice with murine gammaherpesvirus 68 (MHV-68)." (PMID 30237526, 2018). "IFITM1 is thought to play a role in antiproliferation and immune surveillance, and has been shown to restrict infection by numerous viruses." (PMID 28781951, 2017). "Compared with the control shRNA targeting luciferase, the specific shRNAs caused decreased expression of IFITM1, IFITM2, or IFITM3 after ATMUV infection, respectively." (PMID 28473814, 2017). "To confirm the ability of miR-36 to specifically inhibit IFITM1 expression, we monitored the expression of IFITM1 in target cells that were untransfected, transfected with miR-36 mimic, or miR-NC prior to infection." (PMID 29269892, 2017). "It is therefore interesting that IFITM3 seems to be able to inhibit infection by cell surface fusion to an equivalent or greater extent than IFITM1." (PMID 27219333, 2016). "IFITM3‐HA also inhibited SFV infection via plasma membrane fusion in the P1‐ and P2‐ cells to a similar extent to that seen with IFITM1‐HA." (PMID 27219333, 2016). "That IFITM3 can restrict SFV infection by fusion at the cell surface equivalently to IFITM1 suggests that IFITM3 has greater antiviral potency against SFV." (PMID 27219333, 2016). "Infection by SFV fusion at the cell surface was inhibited by IFITM1, but was equally inhibited by IFITM3." (PMID 27219333, 2016). "Overall, despite low levels of cell surface expression, IFITM3‐HA inhibited SFV infection by fusion at the plasma membrane to a similar or greater extent than IFITM1‐HA." (PMID 27219333, 2016). "In response to low path infection, the duck increases expression of both IFITM1 and 2 (~3-fold) in both lung and ileum." (PMID 26238195, 2015). "We pretreated JSRV pseudovirion-bound HTX or HTX/IFITM1 cells with 20 nM bafilomycin A1 (BafA1), followed by a pH-5.0 pulse for 5–10 min; cells were then allowed for infection for 4 h in the presence of BafA1." (PMID 23358889, 2013).
infection (continued). "IFITM1 also moderately, but consistently, inhibited the infection by amphotropic 10A1 MLV pseudovirions (p<0.05), yet IFITM2 and 3 did not inhibit and even somewhat enhanced entry." (PMID 23358889, 2013). "IFITM1 inhibits hMPV infection by blocking the fusion of the viral envelope with the host cell membrane, preventing the virus from entering the cytoplasm and establishing infection." (PMID 40235933, 2025). "They found that IFITM1 similarly enhances infection by EBV and herpes simplex virus 2 (HSV-2)." (PMID 40416980, 2025). "In female mice, there were 430 DEGs in the infection group (FT) compared with the control group (FC), 195 genes with upregulated expression, such as Ifitm1, Wfdc21, Wfdc17, RARα, and Mgam (P < 0.001), and 235 genes with downregulated expression, such as Xpo7 and Hmbs (P < 0.001)." (PMID 40303139, 2024). "In male mice, there were 478 DEGs in the infection group (MT) compared with the control group (MC); 122 genes with upregulated expression, such as Ifitm1, Wfdc21, Wfdc17, and Adam8 (P < 0.001); and 356 genes with downregulated expression, such as Tuba1b and Cox7b (P < 0.001)." (PMID 40303139, 2024). "Then, the expression of IFITM1/2/3 during EMCV infection was also detected." (PMID 37112847, 2023). "IFITM1/3 restricts infection of chicken cells by a range of different viruses, including highly pathogenic avian influenza virus, and expression of chicken galectin-1 (encoded by CG-1B) inhibits Newcastle disease virus adsorption and replication in chicken cells in vitro." (PMID 37954617, 2023). "Indeed, we found that the baseline protein expression levels of cytosolic pattern recognition receptor (PRR) RIG-I, as well as ISGs (MX1 and IFITM1), were significantly elevated prior to secondary infection." (PMID 37190061, 2023). "IFITM1 may function immediately after infection, before an IFN response is induced, thereby upregulating viral RNA replication." (PMID 37252940, 2023). "Furthermore, the ISGs Mx1, RSAD2, and IFITM1 were upregulated early after infection with IAV DIPs compared to infections with YFV or RSV only." (PMID 37766278, 2023). "The intrinsic virus-limiting factor (IFITM1) inhibits infection with a wide variety of viruses." (PMID 35681845, 2022). "IFITM1 expression was induced by 2 log after infection with SARS-CoV and even 3 log for SARS-CoV-2." (PMID 34394046, 2021). "Notably, our data reporting sensitivity of HIV-1 to IFITM1 is supported by previous studies that also observed IFITM1 inhibition of infection/fusion using replication-competent CXCR4-tropic HIV-1 (42, –44, 47)." (PMID 34001619, 2021). "Given the higher susceptibility of KSHV than of RRV to bafilomycin A1, we speculate that a portion of RRV particles fuses at more peripheral sites, where infection is partially restricted by IFITM1 and IFITM3 Y20A and Δ1–21 mutants." (PMID 34933450, 2021). "We asked whether the KRRK basic residues of IFITM1 had an influence on the infection of SeV and AdV." (PMID 32182730, 2020). "This suggests that these genes are not the sole determinants of outcome after RSV infection and that ISGs work in concert to control infection, targeting different aspects of the viral life cycle, with some factors such as IFITM1 controlling entry and others restricting replication within the cell." (PMID 32611756, 2020). "This may in part be due to differences in where the infection is localized, as there are lower levels of Ifitm1 in the liver than in the lung." (PMID 30567988, 2019). "However, mCMV also establishes infection in the spleen after systemic administration, where there is comparable Ifitm1 expression to the lung." (PMID 30567988, 2019).
infection (continued). "Fewer studies have been performed on IFITM1, which can restrict infection by a number of RNA viruses, including hepatitis C virus, sheep Jaagsiekte virus, HIV, Zika virus, and influenza viruses but not Rift Valley fever virus, Sindbis virus, or Semliki Forest virus." (PMID 30567988, 2019). "Having observed that IFITM1 can restrict infection by enveloped RNA and DNA viruses and that sequence alterations in the CIL domain effectively impair function, we investigated whether there are common SNPs in the IFITM1 gene." (PMID 30567988, 2019). "Previous studies have demonstrated that IFITM1 can restrict infection by some RNA viruses." (PMID 30567988, 2019). "To further confirm the role of IFITM1 in suppressing virus production in T cells, we monitored the production of either wild type or nef-deleted HIV-1 NL4-3 virus in multiple cycle infections in a C8166 T-cell line transduced to constitutively over-express IFITM1." (PMID 30266929, 2018). "IFITM1 could be highly induced by interferon‐α and ‐γ in response to infection by pathogens, and demonstrated antiviral activities, such as inhibition of influenza A replication and enveloped virus infection." (PMID 28781951, 2017). "In light of the positive response of goose IFITM1 and IFITM3 to TMUV infection, we speculate that goose IFITM1 and IFITM3 might facilitate IFN-mediated defenses against TMUV." (PMID 28386554, 2017). "In addition, the primary function of IFITM1 to 3 is to block cellular entry and infection against a broad range of viruses." (PMID 28880886, 2017). "However, IFITM3 is more proficient than IFITM1 at preventing infection by the late endosomal- or lysosomal-entering viruses, including IAV and DENV." (PMID 28386554, 2017). "Furthermore, an IFITM3 mutant (Y20A) that is localized to the plasma membrane inhibited infection by cell surface fusion more potently than IFITM1." (PMID 27219333, 2016). "Furthermore, when IFITM3 is relocated to the plasma membrane (IFITM3‐Y20A) greater inhibition of infection was seen compared to IFITM1." (PMID 27219333, 2016). "However, in the P1 set, the difference between infection by plasma membrane fusion of A549 and IFITM1‐HA cells was much greater, arguing that IFITM1‐HA can inhibit plasma membrane fusion to some extent." (PMID 27219333, 2016). "Collectively, these data suggest that the Env protein of HIV-1NL4–3 mediates greater cell-to-cell transmission, a property that may allow HIV-1 to escape IFITM1 inhibition under the virus spread infection condition." (PMID 25738301, 2015). "Similarly, expression of several genes in the canonical IFN signaling pathway, including Ifng, Jak2, Stat1, Stat2, Socs1, Irf1, Irf9, Tap1, Ifitm1, Psmb8, Ifi35, Gas1 and Fit3 were up-regulated during infection by the mutant strain." (PMID 25201772, 2014). "Interestingly, the JSRV pseudovirion infection in HTX cells was inhibited by IFITM1 (p<0.01) to a much greater extent than by IFITM2 and 3 (p<0.01 and p<0.05, respectively)." (PMID 23358889, 2013). "Female homozygous Ifitm1 mutant and wildtype mice were infected with approximately 50,000 wildtype Listeria (L.m.-wt) and on day 3 after infection the number of colony forming units (CFU) was determined in homogenates from infected spleen and liver to analyze primary susceptibility/resistance." (PMID 23115618, 2012). "Further immunological studies on Ifitm1 knockout mice, possibly by exposing these mouse models to different envirotypes, might be required to characterize the role of Ifitm1 in the potential of the lung to respond to an immunological challenge or infection." (PMID 23115618, 2012). "Amazingly, IFITM1, 2 and 3 overexpression not only restricted virus-like particles bearing influenza virus HA proteins, but also blocked infection by particles coated with envelope proteins from three different flaviviruses: West Nile Virus, yellow fever virus, and Omsk hemorrhagic fever virus." (PMID 21994648, 2010).